VCAM1 (vascular cell adhesion molecule 1)
Diseases named in the same sentence as VCAM1 in open-access papers (continued):
Sharing a sentence is not in itself a finding about the gene and the disease.
ischemic stroke (38 papers, 2010 to 2026). A stroke disorder caused by obstruction of blood flow to the brain, due to thrombotic (local blood clot formation) or embolic (due to a blood clot or other material traveling from another site) event. "In the context of ischemic stroke, elevated VCAM‐1 levels have been linked to increased infarct volume and worse neurological outcomes, particularly among individuals with metabolic comorbidities." (PMID 41567175, 2026). "After an ischemic stroke, an insufficient blood supply can cause miR-126 to target vascular cell adhesion protein 1 (VCAM-1), thereby regulating EPC function and angiogenesis." (PMID 40771978, 2025). "Since the severity of carotid atherosclerosis was a useful indicator of the risk of ischemic stroke, the change of adhesion molecule such as VCAM-1 in the common carotid artery was also investigated." (PMID 31827714, 2019). "Inflammatory biomarkers, including interleukins, CRP, and vascular cell adhesion molecule 1, have been demonstrated to have value in the early diagnosis of ischemic stroke and in predicting clinical outcomes." (PMID 41543379, 2026). "Twelve genes have been reported as potential regulators of HT in ischemic stroke in previous studies: Casp3, Csf2, Ctnnb1, Cxcl12, Hif1a, Il1b, Mtor, Ptgs2, Ptprc, Tlr2, Tlr4, and Vcam1." (PMID 40002863, 2025). "VCAM‐1 binds to VLA‐4 to mediate monocyte recruitment and VCAM‐1 levels increase in ischemic stroke." (PMID 37452512, 2023). "Upregulation of soluble VCAM-1 has been demonstrated in patients with ischemic stroke, although evidence is contradictory." (PMID 37660166, 2023). "In this study, we found that 4-EG treatment repressed the expression of ICAM-1, VCAM-1, and E-selectin in brain endothelial cells, and diminished Evans blue leakage in ischemic stroke." (PMID 35860274, 2022). "Using MPIOs conjugated with monoclonal antibodies that targets vascular cell adhesion molecule-1 (VCAM-1) were shown to be effective in defining the “inflammatory penumbra” in ischemic stroke." (PMID 35163328, 2022). "Lastly, we analyzed VCAM1 data in context to related cardiometabolic and inflammatory proteins to elucidate relevant proteomic signaling networks involved in ischemic stroke." (PMID 33971895, 2021). "Vascular cell adhesion molecule 1 (VCAM1) mediates leukocyte-endothelial cell adhesion and has been associated with pathologies such as ischemic stroke." (PMID 33971895, 2021). "ICAM-1, VCAM-1, and E-selectin mRNA levels were significantly attenuated in Poldip2+/− animals following ischemic stroke compared to sham controls." (PMID 33692398, 2021). "Similar to cardiovascular events, studies have investigated the role of VCAM1 in cerebrovascular events including ischemic stroke." (PMID 33971895, 2021). "Adhesion molecules, such as ICAM-1, VCAM-1, and E-selectin, are increased in endothelial cells as a consequence of ischemic stroke and can be released into the blood." (PMID 32595585, 2020). "The endothelial cell adhesion molecules ICAM-1 and VCAM-1 are important for mediation of tissue injury during ischemic stroke." (PMID 32019570, 2020). "This pathophysiological concept is supported by other studies demonstrating the critical role of VCAM-1 dependent T-cells diapedesis in delayed lesion growth after ischemic stroke." (PMID 25505871, 2014). "The antigen presentation capacity of ECs has been studied over the years, yet it remains unclear whether this function, in coordination with the high expression of VCAM‐1, contributes to the infiltration of T cells during the chronic phase of ischemic stroke." (PMID 40421577, 2025). "Recently, the BACTRAC program showed that intracranial VCAM1 at the time of endovascular treatment could predict the ischemic stroke severity." (PMID 36247764, 2022). "Taken together our findings, whether the anti-adhesion therapy of VCAM-1 and E-selectin in ischemic stroke after MT is a possible future area of inquiry." (PMID 36247764, 2022).
ischemic stroke (continued). "Studies have shown that the adhesion molecules, such as E‐selectin, P‐selectin, ICAM‐1, and VCAM-1, are upregulated on the surface of brain endothelial cells within hours after ischemic stroke that promotes the influx of inflammatory cells into the ischemic brain." (PMID 35860274, 2022). "VCAM-1 has been proposed as a therapeutic target in ischemic stroke and traumatic brain injury." (PMID 21967730, 2011). "The endothelial adhesion molecules VCAM-1 and ICAM-1 have been associated with transendothelial diapedesis of leukocytes and subsequent secondary neuroinflammation in various non-inflammatory CNS disorders and particularly experimental ischemic stroke." (PMID 21967730, 2011). "Furthermore, enhanced serum levels of soluble VCAM-1 were reported in patients with ischemic stroke." (PMID 21060661, 2010). "This is especially notable because VCAM-1 has previously been shown to be the key adhesion molecule controlling invasion of lymphocytes to brain lesions after ischemic stroke and might thereby be of relevance in the cascade of lymphocyte invasion and cerebral IFN-γ production after ICH." (PMID 21967730, 2011). "Studies have reported changes in ECs following ischemic stroke, particularly the upregulation of adhesion molecules such as ICAM‐1 and VCAM‐1." (PMID 40421577, 2025). "Published studies have paid little attention to the correlations between Lp-PLA2 activity (or mass) and other ischemic stroke biomarkers, including CRP, MMPs, IL-6, TNF-α, VCAM1, ICAM1, S100B, vWF, BNGF, and MCP1." (PMID 36313479, 2022). "Using MPIOs coupled with monoclonal antibodies targeting vascular cell adhesion molecule-1 (VCAM-1), molecular MRI has provided evidence for the existence of a new concept defined as “inflammatory penumbra” in ischemic stroke." (PMID 34065179, 2021). "We investigated serum concentrations of E-selectin, VEGF-A, VCAM-1, and ICAM-1 in healthy controls and ischemic stroke patients within 8 h of symptom presentation and again at 72 h." (PMID 32595585, 2020). "The levels of VEGF-A, ICAM-1, and VCAM-1 levels increased acutely (<8 h) in the blood of ischemic stroke patients compared to healthy controls, with VEGF-A and VCAM-1 levels also increased at 72 h." (PMID 32595585, 2020). "After ischemic stroke, the expression of intercellular adhesion molecule-1 (ICAM-1), vascular cell adhesion molecule 1 (VCAM1), integrin, and E-selectin is increased, which promotes peripheral immune cell penetration into the brain tissue and aggravates nervous system inflammation." (PMID 37458258, 2023). "Our results showed that ischemic stroke increased the frequency of ICAM-1+, E-selectin+, and VCAM-1+ CD31+ brain endothelial cells in the ipsilateral hemisphere of vehicle-treated MCAO mice compared to that of sham controls and the contralateral hemisphere of vehicle-treated MCAO mice." (PMID 35860274, 2022). "VLA-4 and VCAM-1 is a well-characterized integrin-ligand pair, with VLA-4 being widely expressed on peripheral blood lymphocytes and VCAM-1 expressed in endothelial cells at an upregulated level in ischemic stroke." (PMID 34335623, 2021). "Blood levels of ICAM-1, VCAM-1, and E-selectin were higher in ischemic stroke patients than in TIA patients, without a correlation of infarct volume with functional outcome." (PMID 32595585, 2020). "This is in line with our findings demonstrating significantly increased plasma ICAM-1 and VCAM-1 levels in ischemic stroke patients compared to controls although we observed no change in E-selectin." (PMID 32595585, 2020). "In a rat ischemic stroke model, it inhibited the stimulation of microglia and astrocytes and decreased the expression of TNF-α, IL-1β, ıntercellular adhesion molecule (ICAM)-1, vascular cell adhesion molecule (VCAM)-1, inducible NO synthase (iNOS), and aquaporin-427." (PMID 40498951, 2025).
ischemic stroke (continued). "Six candidate proteins (LBP, VCAM1, FCN2, FBLN1, APOC-I, and APOB) were assessed using individual samples from the CAD and non-CAD ischemic stroke subjects." (PMID 32508734, 2020). "For the first time, differential expressions of apolipoprotein B, apolipoprotein C-I, lipopolysaccharide-binding protein, vascular cell adhesion molecule 1, fibulin-1, and ficolin-2 were confirmed as being significantly upregulated in CAD as compared to non-CAD ischemic stroke subjects." (PMID 32508734, 2020).
gastric cancer (35 papers, 1997 to 2025). A primary or metastatic malignant neoplasm involving the stomach. "Several studies have confirmed that POSTN, MMP9, and VCAM1 are implicated in regulating the incidence and development of solid tumors such as lung cancer, gastric cancer, and rectal cancer." (PMID 35965624, 2022). "Furthermore, VCAM1 derived from cancer-associated fibroblasts (CAFs) interacts with integrin αvβ1/5 in gastric cancer and promotes tumor invasion in the organism." (PMID 35928884, 2022). "Studies have shown that the positive expression rate of ICAM-1 was related with lymph node metastasis and depth of tumor invasion, and the VCAM-1 expression positive gastric cancers were more invasive and were associated with more lymph node metastases than VCAM-1 expression negative ones." (PMID 26847082, 2016). "This aligns with previous findings that H3K18la promotes VCAM1 transcription and recruits M2 macrophages in gastric cancer." (PMID 41399129, 2025). "VCAM1+ CAFs promoted gastric cancer progression and metastasis in vitro and in vivo via direct contact with gastric cancer cells." (PMID 39451241, 2024). "VCAM-1 was released into the blood as sVCAM-1 after cleavage from the cell surface, and serum sVCAM-1 levels were significantly higher in gastric cancer patients than in normal subjects." (PMID 37868703, 2023). "H. pylori infection increases vascular adhesion molecule 1 (VCAM1) expression in CAFs within the TME through activating the JAK/STAT1 pathway, and CAF-derived VCAM1 interacts with integrin αvβ1/5 in gastric cancer cells to trigger cancer invasion." (PMID 35795038, 2022). "Tumor invasion was also described as being promoted by an increased expression of Sh3bp1 and Vcam1 in hepatocellular carcinoma and gastric cancer, respectively." (PMID 36430209, 2022). "Vascular adhesion molecule-1 (VCAM1), a member of the immunoglobulin family of cell-cell adhesion receptors, is expressed aberrantly in some tumor cells, such as renal, breast, or gastric carcinomas." (PMID 33816243, 2021). "Serum concentrations of ICAM-1 and VCAM-1 were significantly elevated in the patients with gastric cancer in comparison with the group of healthy subjects (P < 0.00001 and P < 0.0001 respectively)." (PMID 9400933, 1997). "This interaction suggests that VCAM-1 may serve as a critical mediator in the crosstalk between CAFs and gastric cancer cells, potentially promoting the invasive phenotype of these cells." (PMID 40485724, 2025). "In gastric cancer, lactate within the tumor microenvironment has been shown to promote histone H3 lysine 18 lactylation (H3K18la), which leads to the transcriptional activation of vascular cell adhesion molecule 1 (VCAM1)." (PMID 39456135, 2024). "Furthermore, the overexpression of VCAM1 in gastric cancer cells enhances the expression of CXCL1, which in turn facilitates the migration of mesenchymal stem cells (MSCs) to the tumor tissue." (PMID 39456135, 2024). "Helicobacter pylori increases the expression of VCAM1 in cancer-associated fibroblasts (CAFs) via JAK/STAT1 signaling pathway in gastric carcinoma, and the level of VCAM1 in patients with gastric cancer is positively correlated with tumor progression and a poor prognosis." (PMID 34895252, 2021). "Targeting H3K18 lactylation and VCAM1 could be a potential therapeutic approach for gastric cancer." (PMID 39876839, 2025). "Moreover, the interaction between CAF-derived VCAM1 and integrin αvβ1/5 could promote gastric cancer cell invasion both in vitro and in vivo." (PMID 34895252, 2021). "H3K18la also drives the transcriptional activity of vascular cell adhesion molecule 1 (VCAM1) and then activates the protein kinase B (AKT)- mTORsignaling pathway, thereby promoting gastric cancer development." (PMID 40563450, 2025).
gastric cancer (continued). "Specifically, VCAM1 elevates the expression of CXCL1 via the activation of the AKT-mTOR pathway, which subsequently promotes the recruitment and infiltration of human gastric cancer-derived mesenchymal stem cells and M2 macrophages." (PMID 39876839, 2025). "For example, the lactylation of H3K18 has been shown to enhance the expression of vascular cell adhesion molecule 1 (VCAM1), thereby facilitating the progression and metastasis of gastric cancer through the AKT-mTOR-CXCL1 signaling pathway." (PMID 39876839, 2025). "Specifically, they demonstrated that CAFs secrete vascular cell adhesion molecule 1 (VCAM-1), which engages with the integrin αVβ1/5 on gastric cancer cells, thereby facilitating tumor invasion both in vitro and in vivo." (PMID 40485724, 2025). "In gastric cancer cells, H3K18 lactylation upregulates Vascular cell adhesion molecule-1 (VCAM1) transcription, activating AKT-mTOR signaling to enhance cell proliferation and migration." (PMID 40057816, 2025). "Moreover, the cell adhesion pathway modulates gastric cancer cell sensitivity to cisplatin by regulating adhesion molecules such as Muc-1, ICAM-1, and VCAM-1." (PMID 40069421, 2025). "In GC models, lactate-induced H3K18 lactylation upregulates VCAM1 transcription, activates AKT-mTOR signaling, enhances CXCL1 secretion, and expands GC-derived mesenchymal stem cells and M2 macrophages, collectively accelerating gastric cancer progression." (PMID 40703527, 2025). "Similar to this, VCAM-1 expression was significantly higher in gastric cancer patients with lymph node metastasis than in those without lymph node metastasis." (PMID 26881177, 2016). "Previous studies have shown that H3K18la-mediated VCAM1 expression promotes gastric cancer progression and metastasis via the AKT‒mTOR‒CXCL1 axis; lactic acid accumulation resulting in H3K18la promotes PD-L1 transcription, thereby mediating the immune escape of gastric cancer cells." (PMID 40796546, 2025). "However, although not independent of tumour stage, serum VCAM-1 levels were significant prognostic factors for patient survival in gastric cancer and colorectal cancer." (PMID 26881177, 2016). "Furthermore, VCAM-1 is expressed mainly from CAFs in gastric carcinoma tissues rather than cancer cells." (PMID 19773759, 2009).
colitis (34 papers, 2005 to 2025). Inflammation of the colon. "Despite this, a striking research gap remains in exploring the effects of anti-VCAM-1 therapies in colitis-associated colorectal cancer or as a chemopreventive agent in IBD." (PMID 40095109, 2025). "Endothelial cells enhanced the expression of ICAM-1 and VCAM-1 in the experimental colitis model caused by trinitrobenzene sulfonic acid, increasing leukocyte recruitment to the inflammatory bowel, which was consistent with our result." (PMID 40224490, 2025). "Interestingly, genetic polymorphisms of Vcam-1 expressed in lymphatic vessels, have been shown to be associated with increased disease susceptibility in IL-10KO colitis mice." (PMID 35163775, 2022). "Several clinical studies have investigated the utility of soluble VCAM-1 as a serum biomarker of colitis, with elevated soluble VCAM-1 levels observed in CD and UC patients." (PMID 40095109, 2025). "The upregulation of VCAM-1 on colorectal tumour tissues compared to normal colonic tissues implies the potential utility of anti-VCAM-1 antibodies for visualising not only sites of colitis but also malignant polyps and neoplastic lesions during CRC." (PMID 40095109, 2025). "Following these experiments, long-term treatment of colitic animals with 5F10 anti-VCAM-1 mAb was shown to significantly reduce inflammatory cell infiltrate, macroscopic tissue damage, and colitis symptoms." (PMID 40095109, 2025). "Deletion of GPR4 in mouse models of experimental colitis decreased the expression of the endothelial adhesion molecules, vascular cell adhesion molecule-1 (VCAM1), and E-selectin in the intestinal microvasculature." (PMID 38514581, 2024). "The mRNA expression of IL-1β, IL-18, IL-6, TNF-α, IFN-γ, ICAM-1, and VCAM-1 was markedly (all p < 0.01) up-regulated in DSS-induced colitis group, while the IL-10 expression was significantly (p < 0.01) down-regulated." (PMID 33859564, 2021). "Studies have reported that the elevated levels of adhesion molecules (ICAM-1 and VCAM-1) were founded in the DSS-induced colitis mice." (PMID 33859564, 2021). "Alleviating intestinal inflammation in the DSS-induced colitis mouse model; Attenuating leukocyte infiltration in the colon; Reducing mesenteric lymph node enlargement; Decreasing the expression of VCAM-1, E-selectin, and TNF-α in colon blood vessels." (PMID 33553219, 2020). "GPR4 deletion reduces the expression of endothelial adhesion molecules E-selectin and VCAM-1 in the colon of the DSS-induced colitis mice." (PMID 33553219, 2020). "Vascular cell adhesion molecule-1 (VCAM-1) can be a promising target for colitis study because of its critical role in inflammation development." (PMID 30804723, 2019). "Our purpose in this study was to reveal the colon inflammation activity in colitis model rabbits with the scintigraphy probe of 99mTc-labeled scFv-VCAM-1." (PMID 30804723, 2019). "Researchers have used anti-VCAM-1 monoclonal antibody as a scintigraphy tracer to evaluate rat colitis, and higher radioactivity uptake was observed in the colon of the colitis rats than that of the control animals." (PMID 30804723, 2019). "In our imaging study, the probes of scFv-VCAM-1 detected colitis lesion quickly in SPECT scintigraphy." (PMID 30804723, 2019). "We used DSS and TNBS to induce colitis in rabbits and used the radioactive imaging probe of 99mTc-scFv-VCAM-1 for the surveillance of colitis lesion." (PMID 30804723, 2019). "Remarkable increases in VCAM-1 expression have also been documented in rodent models of chemically induced colitis, as well as in colitis of IL-10 knockout mice." (PMID 31035617, 2019). "During this course, VCAM-1 plays an important role in the mediation of leukocyte adhesion and recruitment, which makes it feasible to detect colitis lesion in our study." (PMID 30804723, 2019).